MET (MET proto-oncogene, receptor tyrosine kinase)
Diseases named in the same sentence as MET in open-access papers (continued):
Sharing a sentence is not in itself a finding about the gene and the disease.
liver cancer (105 papers, 2011 to 2026). An epithelial or non-epithelial malignant neoplasm that arises from the liver. "Similar signaling pathways are activated by binding of MET to its hepatocyte growth factor receptor, which is also often amplified, overexpressed, or mutated in liver cancer." (PMID 33807722, 2021). "In conclusion, our study found that HULC promotes the progression of liver cancer via the HULC/miR-2052/MET axis, providing a potential diagnostic and therapeutic target for HCC." (PMID 31645479, 2019). "Thus, MET deficiency resulted in a marked enhanced efficacy of the chemotherapy-based anti-liver cancer vaccination." (PMID 32764535, 2020). "Liu constructed a CAR structure targeting and recognizing c-MET antigen using lentivirus infection and demonstrated the specificity and effectiveness of c-MET targeting CAR-NK cell immunotherapy in the treatment of human liver cancer in vitro." (PMID 38245520, 2024). "Western blotting verified that the combination treatment of Cabozantinib and IL-32γ overexpression significantly decreased the mTOR-related proteins (p-mTOR, p-4E-BP1, and p-S6 kinase) and MET but increased p-ULK1 in the liver cancer cell lines." (PMID 39519229, 2024). "Cabozantinib, which is a MET inhibitor, inhibits tyrosine kinases, including vascular endothelial growth factor receptors 1, 2, and 3, MET, and AXL, which are implicated in liver cancer progression." (PMID 39519229, 2024). "Animal experiments showed that SS-b2 significantly decreased the levels of MACC1, p-c-MET and p-Akt in tumour tissue transplanted with H22 liver cancer cells in mice, while it increased the expression of p-BAD." (PMID 39544485, 2024). "Activated c-MET plays a pivotal role in promoting liver cancer stemness by upregulating downstream signaling molecules, including extracellular signal-regulated kinase 1/2 (ERK1/2), protein kinase B (AKT), and nuclear factor kappa B (NF-κB)." (PMID 38201226, 2023). "Among all signaling pathways regulating liver cancer development and progression, we have focused on those elicited by the receptor tyrosine kinases (RTKs) MET and Epidermal growth factor receptor (EGFR), and TGF-β." (PMID 38138981, 2023). "EGFR and MET are two molecules of the RTK family that were related to the survival time of liver cancer patients and resistance to targeted therapy in clinical reports." (PMID 35428350, 2022). "The HGF/MET signaling controls autophagy and metabolism to regulate chemoresistance of liver cancer." (PMID 34120890, 2021). "The MET-mTOR-ROS loop acts as a protective checkpoint in liver cancer, and thus this autoregulatory machinery is a promising combinational target for liver cancer therapy." (PMID 33377662, 2020). "In this study, we investigated the regulatory effect and potential mechanism of hepatocyte growth factor receptor (MET, also known as HGFR) on tumor vaccinations for liver cancer in mice." (PMID 32764535, 2020). "Here, we have found the hepatocyte growth factor (HGF) receptor (MET) is required for mTOR activation-stimulated mitochondrial oxidative phosphorylation (OXPHOS) in a phosphorylation-dependent manner in liver cancer." (PMID 33377662, 2020). "Herein, we identify an AKT-independent MET–MTOR signaling pathway useful for determining the efficacy of liver cancer vaccination." (PMID 32764535, 2020). "Specifically, HGF stimulates, whereas MET depletion or inhibition blocks, liver cancer immunogenicity." (PMID 32764535, 2020). "Herein, we demonstrate that MET expression is significantly associated with the immunogenicity of liver cancer in mice and humans, and that MET depletion dramatically enhances the protective efficacy of chemotherapy-based anti-liver cancer vaccination." (PMID 32764535, 2020).
liver cancer (continued). "We also demonstrate that the newly discovered MET–V-ATPase–MTOR signaling pathway more strongly suppresses liver cancer immunogenicity than does the traditional MET–AKT–MTOR pathway." (PMID 32764535, 2020). "c-MET and its ligand, HGF, are frequently overexpressed in liver cancer and in associated metastases." (PMID 32174795, 2020). "The key signal transduction pathways implicated in the pathogenesis of liver cancer include the PI3K/Akt/mTOR pathway, Wnt/β-catenin signalling cascade, and HGF/c-MET pathway." (PMID 21955323, 2011). "Integrin/C-MET targeting leverages OC’s inhibitory effects on c-MET signaling in breast and liver cancers; conjugating nanoparticles with c-MET ligands (e.g., hepatocyte growth factor mimetics) could enhance tumor-specific accumulation." (PMID 40564985, 2025). "Consequently, reversing liver cancer resistance by targeting the c-MET pathway has shown promising results, cabozantinib is a notable success in this regard." (PMID 40426058, 2025). "Cellular mesenchymal-epithelial transition factor (c-MET), also known as hepatocyte growth factor receptor (HGFR), is a crucial receptor tyrosine kinase implicated in various solid tumors, including lung, breast, and liver cancers." (PMID 39664377, 2024). "A compendium of studies has unveiled c-MET’s ability to upregulate programmed cell death-ligand 1 (PD-L1) in diverse cancers, including liver cancer, potentially offering the tantalizing prospect of simultaneous inhibition of c-MET and PD-L1 with c-MET inhibitors." (PMID 39664377, 2024). "Knockdown of integrin β1 could slow down liver cancer progression by inhibiting MET proto-oncogene, receptor tyrosine kinase (MET) and epidermal growth factor receptor signaling." (PMID 38374893, 2024). "To further examine the involvement of the MET pathway with IL-32γ-induced autophagy in liver cancer cell lines, we examined the combination effects of Cabozantinib, a MET inhibiting compound, and IL-32γ overexpression on autophagy induction in liver cancer cell lines." (PMID 39519229, 2024). "Additionally, in liver cancer, c-MET inhibitor was found to stabilize PD-L1, and the combined therapy of c-MET inhibitor capmatinib with anti-PD-1 therapy showed a significantly improved therapeutic outcome." (PMID 39201787, 2024). "Finally, MET abundance was found to be significantly increased as a result of knocking down overexpressed MSI2 in liver cancer cells." (PMID 36599932, 2023). "We next assessed whether the clinical co-existence of high MYC and MET levels in HCC patients is functionally relevant to drive liver cancer." (PMID 36433941, 2022). "Therefore, a drug agent capable of selectively targeting c-MET is promising for liver cancer therapy." (PMID 29899871, 2018). "Despite the role of MET signaling in tumor angiogenesis and the possible therapeutic benefit of targeting MET aberrant expression in liver tumors, the impact of MET inhibition on liver cancer-associated angiogenesis has not been yet adequately reported." (PMID 26413215, 2015). "Moreover, we recently showed that C1GALT1 modifies O-glycans on HGF receptor (MET) to enhance cell proliferation in liver cancer cells." (PMID 24758762, 2014). "In the present study, we found that MET was associated with mTOR analyzed by the STRING method with big database, and the IL-32γ overexpression reduced the mTOR and mTOR-related proteins (p-mTOR, p-4E-BP1, p-S6 kinase) expression but increased p-ULK1 in liver cancer cell lines." (PMID 39519229, 2024). "In addition, the combination treatment of Cabozantinib and IL-32γ overexpression further increased the expression of autophagy-related markers and p-ULK1; however, the expression levels of MET, p-mTOR, and mTOR-related proteins further decreased in liver cancer cell lines." (PMID 39519229, 2024). "Moreover, no mutations in MYC or MET genes are reported in this liver cancer cell panel, except for a MYC missense mutation in HCC1.1 and MET amplification in MHCC97 cells." (PMID 36433941, 2022).
liver cancer (continued). "For example, EGFR and MET core fucosylation can potentiate their ligand binding ability and thus may enhance downstream signaling to support tumor growth and metastasis in liver cancer." (PMID 35303925, 2022). "Unexpectedly, AKT activation did not repress MET deficiency-enhanced liver cancer immunogenicity." (PMID 32764535, 2020). "Conditional depletion of HGF in CAFs resulted in decreased development of liver cancer, and depletion of the HGF receptor MET in hepatocytes or tumour compartments reduced tumour growth." (PMID 39780187, 2025). "As summarized elsewhere, hydrodynamic transfection of MET/CAT with SB is a reliable and widely used method to generate liver cancer in mice." (PMID 37078828, 2023). "We then used Western blot analyses to confirm that when MSI2 was selectively suppressed, MET was also suppressed, and conversely, when MSI2 was overexpressed, the expression of MET was also increased in liver cancer cells." (PMID 36599932, 2023). "The role of C3G/RAPGEF1, required for the proper function of HGF/MET signaling in HCC and HPCs, is highlighted, due to its ability to promote HCC growth and, regulate HPC fate and platelet-mediated actions on liver cancer." (PMID 38138981, 2023). "We detected multiple genomic HBV integrations in two distinct types of liver cancer, with recurrent events at TERT, ZMAT4, MET, ANKFN1, PLXNB2 in ICC, and TERT, ALKBH5 in CHC." (PMID 36123506, 2022). "Liver cancer organoids (n=7) were also subjected to targeted therapies (KRAS, MET and KIT targeting)." (PMID 33816288, 2021). "Following preclinical data demonstrating activity of tepotinib against primary liver cancer explants with MET overexpression, two Phase 1b/2 studies were designed to investigate tepotinib in patients with HCC with MET overexpression." (PMID 33972742, 2021). "Using mouse models of liver cancer induced by tissue-specific overexpression of MYC and MET, the effect of these two oncogenes on metabolic alterations in developed HCC were investigated by Yuneva and collaborators." (PMID 33182674, 2020). "As the alternative name of c-MET indicates, Hepatocyte Growth Factor Receptor (HGFR) has an important role in liver development and regeneration, thus predestinating a pivotal oncogenic driver function of the gene in liver cancer." (PMID 33596971, 2021). "Double-inhibition of MET and MTOR efficiently enhanced liver cancer vaccination in mice." (PMID 32764535, 2020). "Additionally, even though MSI2 target genes, such as MYC, LIN28A, and MET, have been extensively studied, the upstream mechanism driving MSI2 overexpression in liver cancer development remains unclear." (PMID 36599932, 2023). "Interestingly, LECT2 seems to be a tumor suppressor in liver cancer, and it has been reported that LECT2 inhibits HCC progression mediated the blockade of c-MET signaling, tumoral angiogenesis, oncogenic behaviors of cancer cells and high-grade inflammation in HCC." (PMID 36055405, 2022). "Therefore, we investigated whether a combined treatment of MET and MTOR inhibitors can synergistically inhibit liver cancer cells in vitro." (PMID 32764535, 2020). "Importantly, compound 13h showed the highest anti-proliferation activity against Hep-G2 with IC50 of 1.7 μM, which is better than the c-MET inhibitor XL184, suggesting that compound 13h may have great potential for liver cancer therapy." (PMID 27187326, 2016). "Furthermore, based on c-MET contributes to the aggressiveness of HCC, this correlation might further indicate that MACC1 enhances the invasiveness of liver cancer cells." (PMID 21955323, 2011).
liver cancer (continued). "Besides, the activities of c-MET and β-catenin signaling were not significantly and negatively correlated with the differentiation status and LECT2 expression in liver cancer cells." (PMID 36055405, 2022). "Mechanistically, MET repressed liver cancer immunogenicity independent of the traditional PI3K–AKT cascade, and MET interacted with vacuolar ATP synthase (V-ATPase) and mediated the activation of mammalian target of rapamycin (MTOR), thus suppressing liver cancer immunogenicity." (PMID 32764535, 2020).
osteosarcoma (91 papers, 2003 to 2025). A usually aggressive malignant bone-forming mesenchymal neoplasm, predominantly affecting adolescents and young adults. "The analysis included allelotyping, real-time quantitative polymerase chain reaction (qPCR), gene sequencing, and protein polymorphism study for MET in 91 osteosarcoma cases." (PMID 38596618, 2024). "To validate the data we obtained, we analyzed the expression of c-MET, a gene that has been often associated with osteosarcoma." (PMID 30261649, 2018). "MET shows therefore an increasingly important role in osteosarcoma, as its overexpression seems to be linked to migration and invasion of CSC." (PMID 27851822, 2016). "Mutant c-MET was also found to be associated with the aggressive phenotype of osteosarcomas." (PMID 40361420, 2025). "These AS1411—SL1 chimeras are likely to be promising c-MET degraders in osteosarcoma targeted therapy." (PMID 41247642, 2025). "Osteosarcoma (OS) is the most common malignant bone tumor, and c-MET is a recognized therapeutic target." (PMID 41247642, 2025). "The first MET gene fusion, a TPR-MET fusion, was first identified in a human osteosarcoma cancer cell line treated with a chemical mutagen." (PMID 40361420, 2025). "The MET RTK was initially discovered as a transforming oncogene in human osteogenic sarcoma cell lines exposed to the chemical carcinogen N-methyl-N'-nitro-N-nitrosoguanidine (MNNG), from which it derives its name ‘MET’." (PMID 40924941, 2025). "We have confirmed the sensitivity of MET-overexpressing osteosarcoma cells to MET inhibitors in vitro and successfully enhanced their response to Anlotinib." (PMID 39605750, 2024). "The aim of this study is to explore the therapeutic potential of combining MET inhibitors with Anlotinib for the treatment of Anlotinib-resistant osteosarcoma." (PMID 39605750, 2024). "Lipocalin-2 suppresses osteosarcoma cell metastasis by inhibiting MET expression via the MEK/ERK pathway." (PMID 38816365, 2024). "This review summarizes 3 decades’ worth of research on MET’s involvement in osteosarcoma and further explores its potential as a therapeutic target for patients with this disease." (PMID 38596618, 2024). "A distinct approach was taken by Natacha Entz-Werle and colleagues to investigate the role of MET activation in osteosarcoma." (PMID 38596618, 2024). "One study examined frozen samples from 87 primary bone and soft tissue tumors and found that osteosarcoma exhibited the highest levels of MET/HGF expression." (PMID 38596618, 2024). "The findings of this study confirm that the heat shock protein inhibitor 17-DMAG effectively inhibits the proliferation of osteosarcoma cells and induces apoptosis by targeting MET." (PMID 38596618, 2024). "Several investigations have aimed to understand the genetic and functional changes of the HGF/MET pathway in human osteosarcoma, considering its crucial role in regulating cell proliferation and apoptosis in the liver." (PMID 38596618, 2024). "To explore the possibility of magnetic-driven hydrogel microrobots loaded with MET inhibitors in enhancing the efficacy of TKI targeted drugs against osteosarcoma, we have chosen SCR1481B1, a MET inhibitor, as the research drug." (PMID 39605750, 2024). "Abnormal activation of MET is commonly observed in osteosarcoma patients, and MET inhibitors are acknowledged for their potential to suppress tumors." (PMID 38596618, 2024). "In this review, we explore the current biological evidence regarding MET in osteosarcoma and discuss its potential as a therapeutic target for osteosarcoma patients." (PMID 38596618, 2024). "Molecular pathology and cancer biology data suggest that HGF/MET signaling plays a crucial role in the survival, growth, proliferation, metastasis, and drug resistance of osteosarcoma." (PMID 38596618, 2024). "Both wild-type and persistently activated MET overexpression have been shown to induce human primary osteoblasts into osteosarcoma." (PMID 38596618, 2024).